EIF5 (eukaryotic translation initiation factor 5)
Description:
Component of the 43S pre-initiation complex (43S PIC), which binds to the mRNA cap-proximal region, scans mRNA 5'-untranslated region, and locates the initiation codon. In this complex, acts as a GTPase-activating protein, by promoting GTP hydrolysis by eIF2G (EIF2S3). During scanning, interacts with both EIF1 (via its C-terminal domain (CTD)) and EIF1A (via its NTD). This interaction with EIF1A contributes to the maintenance of EIF1 within the open 43S PIC. When start codon is recognized, EIF5, via its NTD, induces eIF2G (EIF2S3) to hydrolyze the GTP. Start codon recognition also induces a conformational change of the PIC to a closed state. This change increases the affinity of EIF5-CTD for EIF2-beta (EIF2S2), which allows the release, by an indirect mechanism, of EIF1 from the PIC. Finally, EIF5 stabilizes the PIC in its closed conformation.
Synonyms: eIF-5; EIF-5A
Tractability: Small molecule: a structure with a bound ligand is known; it has a binding pocket of medium quality. Antibody: its Gene Ontology location is reachable by antibodies, with high confidence. PROTAC: UniProt records ubiquitination sites on it; ubiquitination databases record sites on it; its protein half-life has been measured.
Gene: Protein-coding gene on chromosome 14 (103,333,544 to 103,345,025, forward strand). Ensembl gene ENSG00000100664.
Subcellular location: Cytoplasm
Subcellular location (Human Protein Atlas): Cytosol; Plasma membrane; Primary cilium; Primary cilium tip
Pathways (Reactome):
Metabolism of proteins: GTP hydrolysis and joining of the 60S ribosomal subunit; Ribosomal scanning and start codon recognition
Gene Ontology:
Molecular function: cadherin binding; protein binding; RNA binding; eukaryotic initiation factor eIF2 binding; GDP-dissociation inhibitor activity; translation initiation factor activity
Biological process: regulation of translational initiation; ribosome assembly; formation of cytoplasmic translation initiation complex; translational initiation
Cellular component: cytoplasm; nucleus; cytosol; synapse
Genetic constraint (gnomAD): Loss-of-function variants: 10 observed, 48.91 expected, observed/expected ratio (o/e) 0.2, 90% interval 0.12 to 0.35. The synonymous counts are far from expectation, so gnomAD's model fits this gene poorly and the ratio says little. Missense variants: 396 observed, 556.88 expected, observed/expected ratio (o/e) 0.71, 90% interval 0.65 to 0.77. Synonymous variants: 237 observed, 180.86 expected, observed/expected ratio (o/e) 1.31, 90% interval 1.18 to 1.46.
Homologues: Orthologues: chimpanzee EIF5 (99% identical), macaque EIF5 (99% identical), dog EIF5 (97% identical), mouse Eif5 (97% identical), guinea pig EIF5 (97% identical), rat Eif5 (97% identical), rat Eif5-ps1 (93% identical), tropical clawed frog eif5 (85% identical), zebrafish eif5 (75% identical), Drosophila melanogaster eIF5 (54% identical), Caenorhabditis elegans C37C3.2 (49% identical).
Diseases named in the same sentence as EIF5 in open-access papers:
EIF5 is named in the same sentence as 38 diseases in open-access papers, as found by Europe PMC text mining. Sharing a sentence is not in itself a finding about the gene and the disease. The quoted sentences say what the papers report.
glioma (3 papers, 2019 to 2021). A benign or malignant brain and spinal cord tumor that arises from glial cells (astrocytes, oligodendrocytes, ependymal cells). "eIF5 expression showed a high variability throughout all samples and eIF6 (IV: p < 0.01) expression was only elevated in high grade gliomas (HGGs) compared to CCBT." (PMID 33807050, 2021). "Finally, we have analyzed EIF5 and EIF5B expression in gliomas and found that EIF5 is downregulated in astrocytomas and in GBM, only for the mesenchymal and proneural subtypes." (PMID 31795417, 2019). "Protein and mRNA expressions of eIF3B, eIF3I, eIF4A1, eIF4H, eIF5 and eIF6 were significantly increased in high grade gliomas compared to CCBT and partially in low grade gliomas." (PMID 33807050, 2021).
hepatocellular carcinoma (3 papers, 2007 to 2024). A malignant tumor that arises from hepatocytes. "Golob-Schwarzl and colleagues demonstrated that eIF5 has the potential as a biomarker to indicate whether there is virus infection in hepatocellular carcinoma (HCC) tissue." (PMID 33066449, 2020).
astrocytoma (2 papers, 2019 to 2021). "eIF5 (p < 0.05) and eIF6 (p < 0.001) protein levels also varied within astrocytoma sample and significantly increased protein levels were only detected in GBM patients compared to CCBT." (PMID 33807050, 2021). "Besides the already known eIFs, we demonstrated significantly elevated protein levels of eIF3D, eIF3H, eIF3I, eIF3M, p-eIF4G, eIF4H, eIF5 and eIF6 in astrocytoma tissue compared to CCBT." (PMID 33807050, 2021).
hepatitis B (2 papers, 2019 to 2023). "It was shown that eIF5 is regulated by circ_100338/miR-141-3p/RHEB axis and higher expression of RHEB or eIF5 was an indicator of shorter OS in hepatitis B-related HCC." (PMID 37511619, 2023). "Finally, correlation analysis of RHEB and EIF5 expression with clinicopathological parameters of HCC patients revealed that the circRNA-100338, RHEB, and EIF5 were indicators of poor prognosis in hepatitis B-related HCC." (PMID 31157168, 2019). "Particularly, the pulmonary metastasis rate was higher, and the overall survival was shorter in hepatitis B-related HCC with elevated expression of one or both of RHEB and EIF5 (P < 0.001)." (PMID 31157168, 2019). "In accordance with experiments in vitro, hepatitis B-related HCC tissues in circRNA-100338-high group also showed elevated expression of both RHEB, mTORC1, and EIF5, further demonstrating that circRNA-100338 could promote activation of mTOR signaling pathway." (PMID 31157168, 2019).
lung carcinoma (2 papers, 2019 to 2022). "Histone deacetylase 2 can regulate the expression of eIF5 in lung cancer, and its high expression is associated with a poorer prognosis in lung cancer patients." (PMID 36360287, 2022). "Interestingly, we previously noted that high expression of 5MP1, but not that of 5MP2, correlates with poorer prognosis of breast and lung cancer patients, while in contrast, high expression of eIF5 correlates with their better prognosis." (PMID 31175057, 2019).
schizophrenia (2 papers, 2023 to 2026). A major psychotic disorder characterized by abnormalities in the perception or expression of reality. "Placentae from ∆9-tetrahydrocannabinol-exposed males and females revealed altered expression of genes previously identified in human transcriptomic datasets of schizophrenia (i.e., Furin, Rccd1, and Atp5mk), with some expression changes being sex-specific (i.e., Eif5, Rps10, Vps33b, and Iqgap1)." (PMID 40827685, 2026).
asthma (1 paper, 2026). "Differentially methylated loci were near genes related to asthma (ITPR2, MAPK1), lung function (FKBP11), mitochondrial function (MRPL20, SPTBN1), inflammation (C3), and immune function (N4BP3, EIF5)." (PMID 41749276, 2026).
Babesia infection (1 paper, 2022). "miR-5787 has been implicated in inhibition of eIF5 in fibroblasts, but their significance in Babesia infection is yet unknown." (PMID 36275032, 2022).
breast carcinoma (1 paper, 2014). "Here, we found that translation initiation factor eIF4E1, but not eIF4E2, eIF4G1, eIF1A, eIF2α, or eIF5, is significantly enhanced in breast CSCs in comparison to non-CSC breast cancer cells." (PMID 25115391, 2014). "We found that eIF4E1 (also named eIF4E), but not eIF4E2, eIF4G1, eIF1A, eIF2α, or eIF5, is significantly increased in BCSCs, in comparison to SKBR-3, MCF-7 and MDA-MB-231 breast cancer cells and non-BCSCs of HMLER (CD44high/CD24low)SA cells." (PMID 25115391, 2014).
Cerebral ischemia (1 paper, 2024). Restriction of arterial blood supply to the brain associated with insufficient oxygenation to support the metabolic requirements of the tissue. "Our results demonstrated that LINC00894 regulated cerebral ischemia injury by stabilizing EIF5 and facilitating EIF5-ATF4-dependent induction of FGF21 and ACOD1." (PMID 39060766, 2024). "Using MCAO and in vitro ischemia models, we showed that LINC00894 stabilized EIF5 to enhance the expression of ATF4, which transcriptionally regulated the expression of FGF21 and ACOD1, thus protecting cells from brain ischemia-induced damage." (PMID 39060766, 2024).
colon carcinoma (1 paper, 2017). "In situ detection confirmed an overexpression at the mRNA level of eIF1 and eIF5 in colon carcinoma vs. NNT (p<0.001 and p<0.05)." (PMID 29254159, 2017).
cyst (1 paper, 2022). A sac-like closed membranous structure that may be empty or contain fluid or amorphous material. "Our study revealed that translation initiation factor eIF5, together with its co-regulators eIF1A and eIF2γ, acted in the CySC lineage to mediate both cyst cell and germ cell differentiation and maintained the balance of proliferation and cell death." (PMID 35883200, 2022). "First of all, we analyzed the testicular eIF5 expression pattern via single nucleus RNA sequencing (snRNA-seq) data and found that eIF5 was widely expressed in Drosophila testes, especially in germ cells and cyst cells." (PMID 35883200, 2022). "There was a dramatic increase in Eya-positive cyst cells in Tj > eIF5 OE testes compared with those in the controls." (PMID 35883200, 2022). "We provided evidence that eIF5 in CySC lineage, together with eIF1A and eIF2γ, promotes cyst cell and germ cell differentiation, which ultimately prevent the formation of TGCTs." (PMID 35883200, 2022). "Reducing the eIF5 level using Tj-Gal4 led to the formation of tumorlike structures, and both cyst cell and germ cell differentiation were defective." (PMID 35883200, 2022). "In Tj > eIF5 RNAi testes, cyst cells were arrested at the CySC stage, while the accumulated GSC-like masses were blocked at mitotic spermatogonia stage." (PMID 35883200, 2022). "Our data strongly suggested that eIF5, eIF1A, and eIF2γ prevent the formation of TGCTs by cyst cell and germ cell differentiation via the pre-initiation complex." (PMID 35883200, 2022). "Our study investigated roles of translation initiation factor eIF5 in Drosophila testes systemically and uncovered that CySC lineage eIF5 was essential for cyst cell differentiation, which then promoted germ cell differentiation via non-autonomous cell effects." (PMID 35883200, 2022). "Among testes with morphological structures, we observed that the number of CySCs and mature cyst cells could be recovered in Tj > eIF5 OE; eIF5 RNAi testes." (PMID 35883200, 2022). "However, the accumulation of undifferentiated cyst cells and germ cells was observed and mature cyst cells were totally lost in testes at 9 and 15 days (29 °C) after knockdown of eIF5 by Ptc-Gal4." (PMID 35883200, 2022). "In the genetic interaction analysis, we showed that CySCs and mature cyst cells patterns could be rescued in Tj > eIF5 OE; eIF1A RNAi and Tj > eIF5 OE; eIF2γ RNAi testes." (PMID 35883200, 2022). "Furthermore, we detected whether proliferation was affected by the ectopic expression of eIF5 in cyst cells." (PMID 35883200, 2022). "Next, we asked whether translation initiation factor eIF5 affected cyst cell division." (PMID 35883200, 2022). "Here, we demonstrated that in CySCs, translation initiation factor eIF5 mediates cyst cell differentiation and the non-autonomously affected germ cell differentiation process." (PMID 35883200, 2022). "In this study, we found that cyst cells lacking eIF5, eIF1A, and eIF2γ, which are key components of the pre-initiation complex, mimicked the phenotype of cells lacking several small ribosomal subunits for germ cell differentiation." (PMID 35883200, 2022). "Taken together, these results suggested that eIF5 could regulate cyst cell differentiation and then provide non-autonomous signals for germ cell differentiation in adult testes." (PMID 35883200, 2022). "To investigate whether a lack of eIF5 could block cyst cell and germ cell differentiation at the adult stage, we manipulated eIF5 expression at the early stage of cyst cells driven by Ptc-Gal4, UAS-GFP; tub-Gal80ts fly strain." (PMID 35883200, 2022).
endometrial cancer (1 paper, 2019). Primary or metastatic malignant neoplasm involving the endometrium (mucous membrane that lines the endometrial cavity). "We further investigated the expression patterns of peIF2α, eIF2α, eIF3c, eIF3h, eIF4e, eIF4g, eIF5 and eIF6 in endometrial cancer compared to non-neoplastic patient samples using immunoblot analysis." (PMID 31817792, 2019).
glaucoma (1 paper, 2020). Increased pressure in the eyeball due to obstruction of the outflow of aqueous humor. "It is important to note that some of our positional candidates—Eif5, Bag5, Klc1, and Ppp1r13b—have been previously demonstrated to play a role in glaucoma and/or RGC health." (PMID 32174956, 2020).
glioblastoma multiforme (1 paper, 2021). "Particularly, eIF5B, a subunit of eIF5, has been found to promote the translation of pro-survival and anti-apoptotic proteins in glioblastoma multiforme cell lines but has never been studied in prostate cancer." (PMID 34525951, 2021).
Infertility (1 paper, 2024). "In summary, these results indicate that Eif5 deletion in oocytes impairs follicle development, leading to infertility." (PMID 39113233, 2024).
Obesity (1 paper, 2021). Accumulation of substantial excess body fat. "An even more pronounced reduction was observed for Eif5, whereas expression of Tcf25 and Bin1 were not altered by diet-induced obesity." (PMID 33257475, 2021).
prostate adenocarcinoma (1 paper, 2025). "It was determined that 21 proteins (DHX9, EIF5, HPRT1, INPP5B, MCM6, PPP6C, SYF2, etc.)whose expression was increased in PC3‐R cells based on label‐free nLC‐MS/MS analysis were consistent with both TCGA prostate adenocarcinoma N0 and N1 nodal metastasis status and correlation data." (PMID 39799471, 2025).
rectal tumors (1 paper, 2019). "CYT-high rectal tumors on the other hand, had recurrent deletions at loci 3p21.31 (RHOA), 5q22.2 (APC), 10q26.2 (MGMT), 14q32.2 (AKT1, EIF5, YY1), 18q21.2 (SMAD4, MAPK4), and a single amplification in 7p15.3 (STK31)." (PMID 31429779, 2019).
testicular germ cell tumor (1 paper, 2022). A germ cell tumor arising from the testis. "CySCs lacking eIF5 displayed unbalanced cell proliferation and apoptosis, forming testicular germ cell tumors (TGCTs) during spermatogenesis." (PMID 35883200, 2022).
Turner syndrome (1 paper, 2024). Turner syndrome is a chromosomal disorder associated with the complete or partial absence of an X chromosome. "A recent clinical study reports that patients with Turner syndrome show a lack of a cluster of oogonia with high EIF5 expression and germ cell apoptosis at 12–13 weeks post‐conception, subsequently developing POI after birth." (PMID 39113233, 2024).
viral infection (1 paper, 2021). "Accordingly, eIF5 was particularly upregulated in the late phase after viral infection, consistent with the previous reports that the increase of eIF5 level promotes noncanonical TI61,62." (PMID 34433827, 2021).
tumor (10 papers, 2007 to 2024). "Proportions of eIF5 levels in tumor tissues and NNT are shown using three-stage staining score (lower)." (PMID 31175057, 2019). "(a-b) Kaplan-Meier curves for the overall survival of CRC patients in the TCGA COADREAD dataset (N = 620), classified according to the 5MP2 mRNA expression levels (a) and eIF5 mRNA expression levels (b) in tumor tissues." (PMID 31175057, 2019). "eIF5 overexpression has been reported in different cancer types and is considered to be a predictive tumor marker." (PMID 29254159, 2017). "Tumour growth was associated with decreases in mTOR and p70S6K1 gene expression, as well as reduced expression of eIF4E, eIF5 and eIF2a, three factors involved in protein synthesis (the tumour effect was highly significant at P < 0.05)." (PMID 26847205, 2016). "Tumor size-related proteins were involved in angiogenesis (VCAN, VTN, NRP1), EMT (FN1, CD44, THBS2), and translation (EIF1AX, EIF5), further indicating the biological basis of ccRCC growth." (PMID 37460463, 2023). "The eukaryotic translation initiation factors, namely, EIF1, EIF3E, EIF3H, EIF4G2, EIF5, and EIF6, were all upregulated in the brain metastasis-derived tumor cells." (PMID 33170151, 2020). "BCAT1 suppression in SKOV3 cells led to the induction of several gene nodes (EIF5A2, EIF5 and EIF4H), as part of the eukaryotic initiation factors (eIFs) network, shown to display all elements of a complete oncogenic, as well as tumor suppressive cascade." (PMID 26372729, 2015). "Furthermore, the eIF5 DNA copy is significantly more often deleted, and eIF5 expression is significantly lower in CRC tissues than in NNT, regardless of primary sites or tumor grades." (PMID 31175057, 2019). "4EGI-1 treated tumor cells presented decreased CSC pluripotency markers NANOG and OCT4, tumor metastasis regulator CXCR4, EMT mediator c-MYB and proangiogenic factor VEGF, but not translation initiation factors eIF1A or eIF5, comparing to vehicle treated breast CSC tumor cells in vivo." (PMID 25115391, 2014).
cancer (9 papers, 2007 to 2025). A tumor composed of atypical neoplastic, often pleomorphic cells that invade other tissues. "eIF5B, eIF5, and eIF5A all contain links into hallmark stages and mechanisms of cancer proliferation, and manipulation of these proteins offers a potential regulation point of gene expression regulation." (PMID 28083147, 2016). "It enhances cancer cell proliferation and invasion by regulating eIF5 (eukaryotic translation initiation factor 5) and eIF6, thus adversely affecting patient prognosis." (PMID 40083325, 2025). "EIF5 facilitates protein synthesis and cellular proliferation, aligning with its established oncogenic roles in various cancers." (PMID 40936684, 2025). "EIF5 not only plays an important role in the initiation of translation of some proteins but also regulates the occurrence of cancer and promotes cell proliferation, senescence, and apoptosis." (PMID 32554864, 2020). "The expression of eIF5 has been shown to be upregulated in many cancer entities and is thought to play a role in the regulation of cell proliferation and apoptosis." (PMID 29254159, 2017). "Since both CK2 and eIF5 are frequently overexpressed in different cancer types, their interaction might contribute to an accelerated cell cycle transition and thus to proliferation." (PMID 36009534, 2022). "CK2s phosphorylation targets include deleted in breast cancer 1 (DBC1), eIF5, and endothelin-converting enzyme-1c (ECE-1c), which promote cancer cell invasion and progression." (PMID 28083147, 2016).
diseases of the central nervous system (1 paper, 2025). "These include genes involved in neurodegeneration (EIF5), diseases of the central nervous system (IPO13, ST3GAL3), tobacco addiction (CHRNB4, PSMA4), fatty acid metabolism (ACSBG1), and skin conditions (HYI, ELOVL1)." (PMID 40074595, 2025).
EIF5 also shares sentences with these, for which no sentence is quoted: infection (2 papers); breast tumors (1); colorectal cancer (1); diabetes (1); esophageal squamous cell carcinoma (1); ischemia (1); lymphoma (1); neuroblastoma (1); ovarian carcinoma (1); preeclampsia (1); prostate carcinoma (1); rectum cancer (1); uveal melanoma (1).